HDAC10 (histone deacetylase 10)
Description:
Polyamine deacetylase (PDAC), which acts preferentially on N(8)-acetylspermidine, and also on acetylcadaverine and acetylputrescine. Exhibits attenuated catalytic activity toward N(1),N(8)-diacetylspermidine and very low activity, if any, toward N(1)-acetylspermidine. Histone deacetylase activity has been observed in vitro. The physiological relevance of protein/histone deacetylase activity is unclear and could be very weak. May play a role in the promotion of late stages of autophagy, possibly autophagosome-lysosome fusion and/or lysosomal exocytosis in neuroblastoma cells. May play a role in homologous recombination. May promote DNA mismatch repair.
Synonyms: HD10; DKFZP761B039
Tractability: Small molecule: an approved drug acts on it; a high-quality ligand is known; it belongs to a druggable protein family. PROTAC: ubiquitination databases record sites on it; a small molecule that binds it is known. Other modalities: an approved drug acts on it.
Target class: HDAC class IIb; Epigenetic regulator; Eraser; Histone deacetylase
Chemical probes: DKFZ-748 (high quality), PD134228, PD134230, PD134232, TH65 (high quality), Tubastatin-A (high quality)
Gene: Protein-coding gene on chromosome 22 (50,245,183 to 50,251,405, reverse strand). Ensembl gene ENSG00000100429.
Subcellular location: Cytoplasm; Nucleus
Subcellular location (Human Protein Atlas): Nucleoplasm; Cytosol; Vesicles
Pathways (Reactome):
Disease: Constitutive Signaling by NOTCH1 HD+PEST Domain Mutants; Constitutive Signaling by NOTCH1 PEST Domain Mutants
Chromatin organization: HDACs deacetylate histones
Developmental Biology: Differentiation of naive CD4+ T cells to T helper 2 cells (Th2 cells)
Gene expression (Transcription): Notch-HLH transcription pathway
Signal Transduction: NOTCH1 Intracellular Domain Regulates Transcription
Gene Ontology:
Molecular function: acetylputrescine deacetylase activity; acetylspermidine deacetylase activity; deacetylase activity; enzyme binding; histone deacetylase activity; histone deacetylase binding; protein binding; protein lysine deacetylase activity; zinc ion binding
Biological process: homologous recombination; macroautophagy; negative regulation of DNA-templated transcription; negative regulation of transcription by RNA polymerase II; positive regulation of mismatch repair; regulation of DNA-templated transcription; chromatin organization; chromatin remodeling
Cellular component: cytoplasm; cytosol; histone deacetylase complex; nucleoplasm; nucleus
Genetic constraint (gnomAD): Loss-of-function variants: 89 observed, 81.46 expected, observed/expected ratio (o/e) 1.09, 90% interval 0.92 to 1.3. The upper end of that interval is the gene's LOEUF score, 1.3, which puts it in group 5 of 6, group 1 being the genes least tolerant of losing a copy. Missense variants: 924 observed, 854.53 expected, observed/expected ratio (o/e) 1.08, 90% interval 1.02 to 1.14. Synonymous variants: 450 observed, 386.66 expected, observed/expected ratio (o/e) 1.16, 90% interval 1.08 to 1.26.
Homologues: Orthologues: chimpanzee HDAC10 (99% identical), macaque HDAC10 (95% identical), pig HDAC10 (79% identical), mouse Hdac10 (75% identical), dog HDAC10 (73% identical), rat Hdac10 (72% identical), rabbit HDAC10 (65% identical), zebrafish hdac10 (45% identical), Caenorhabditis elegans hda-10 (24% identical). Paralogues in human: HDAC6 (40% identical), HDAC4 (20% identical), HDAC9 (18% identical), HDAC7 (17% identical), HDAC5 (17% identical), HDAC1 (8% identical), HDAC2 (7% identical), HDAC3 (7% identical), HDAC8 (6% identical), HDAC11 (6% identical).
Diseases named in the same sentence as HDAC10 in open-access papers:
HDAC10 is named in the same sentence as 71 diseases in open-access papers, as found by Europe PMC text mining. Sharing a sentence is not in itself a finding about the gene and the disease. The quoted sentences say what the papers report.
neuroblastoma (28 papers, 2014 to 2025). Neuroblastoma (NB) is the most common solid, extracranial childhood tumor. "For instance, studies in neuroblastoma have demonstrated that HDAC10 loss disrupts autophagy and sensitizes cancer cells to chemotherapy, underscoring its role in promoting survival under therapeutic stress." (PMID 39958888, 2025). "Diseases associated with HDAC10 include Neuroblastoma, renal cell carcinoma and lung adenocarcinoma." (PMID 34777208, 2021). "We have previously identified HDAC10 as a poor prognostic marker in high-risk neuroblastoma, where it promotes chemoresistance via autophagy, lysosomal exocytosis and DNA double-strand break repair." (PMID 33923163, 2021). "Increased HDAC10 expression has been associated with several malignancies, including lung and gastric cancer and neuroblastoma, and was been linked with poor outcomes." (PMID 31949209, 2020). "High HDAC10 expression is also associated with ATGs gene expression in neuroblastoma but also to poor prognosis." (PMID 31861179, 2019). "In childhood tumors of the nervous system (neuroblastoma and medulloblastoma), elevated HDAC10 expression is associated with poor outcome of treated patients." (PMID 25915736, 2015). "In contrast to HDAC6, which is an acetyl lysine deacetylase, HDAC10 is a N8-acetylspermidine deacetylase and has been linked to dysregulated polyamine metabolism and neoplastic disorders such as colon cancer, prostate cancer, and neuroblastoma." (PMID 39409979, 2024). "Further studies also suggest that the class IIb HDAC sub-family member, HDAC10 may exert specific roles in neuroblastoma progression, as elevated HDAC10 expression has previously been associated with poor clinical outcomes in high risk neuroblastoma patients." (PMID 33117806, 2020). "Additionally, research into HDAC10 targeting has led to the creation of specific inhibitors, like Tubastatin A and its analogues, aiming for precise action against HDAC10, which is linked to poor prognosis in neuroblastoma." (PMID 38654286, 2024). "Compounds that specifically inhibit HDAC10 are expected to become more effective anticancer drugs to help people treat neuroblastoma, which is resistant to chemotherapy." (PMID 36227941, 2022). "The presence of tubastatin A in the Huh7-luc/neo cells led to accumulation of lysosomes as a visible result of the inhibition of HDAC10, which has previously been described for neuroblastoma cells." (PMID 33925399, 2021). "It has been reported that depletion or inhibition of HDAC10 results in the accumulation of lysosomes in neuroblastoma cell lines." (PMID 33925399, 2021). "Clinical analysis has also highlighted the significant correlation between HDAC8 and HDAC10 expression and patient outcome, suggesting their potential utility as predictive biomarkers of therapeutic response to HDACi in neuroblastoma." (PMID 33117806, 2020). "We have previously identified high HDAC8 and HDAC10 expression to correlate with poor outcomes in neuroblastoma and high-grade neuroblastoma, respectively." (PMID 29947893, 2018). "Doxorubicin-induced DSBs are indeed strongly enhanced after tubastatin A co-treatment and tubastatin A alone is sufficient to increase DSBs in neuroblastoma cells, supporting recent studies that demonstrate a role for HDAC10 in DNA repair." (PMID 29968769, 2018). "HDAC10 expression strongly correlates with poor overall survival in high-grade (INSS stage 4) neuroblastoma, making this HDAC a particularly attractive druggable target in this entity." (PMID 29947893, 2018). "HDAC10 supports neuroblastoma cell survival by promoting autophagic flux, and inhibition of HDAC10 sensitizes chemotherapy-resistant cells to treatment with DNA damage-inducing drugs such as doxorubicin." (PMID 29947893, 2018). "Here, we further unravel the role of HDAC10 in lysosome-coupled mechanisms, such as lysosomal exocytosis, which plays a critical role in neuroblastoma resistance against doxorubicin." (PMID 29968769, 2018).
neuroblastoma (continued). "We have shown before that amongst other HDACs, HDAC10 plays a pivotal role in neuroblastoma chemoresistance and inhibition of HDAC10 displayed promising anti-tumor effects." (PMID 29968769, 2018). "Increased doxorubicin accumulation after HDAC10 inhibition cannot be solely responsible for the sensitization of neuroblastoma cell lines to doxorubicin." (PMID 29968769, 2018). "Here, we show that depleting or inhibiting HDAC10 results in accumulation of lysosomes in chemotherapy-resistant neuroblastoma cell lines, as well as in the intracellular accumulation of the weakly basic chemotherapeutic doxorubicin within lysosomes." (PMID 29968769, 2018). "High histone deacetylase (HDAC) 8 and HDAC10 expression levels have been identified as predictors of exceptionally poor outcomes in neuroblastoma, the most common extracranial solid tumor in childhood." (PMID 29947893, 2018). "Here, we demonstrate that HDAC10 is important for lysosomal exocytosis in neuroblastoma cell lines and that chemoresistant neuroblastoma cells use this mechanism to dispose of chemotherapeutics such as doxorubicin." (PMID 29968769, 2018). "We demonstrated that HDAC8 inhibits neuroblastoma cell differentiation and HDAC10 promotes autophagy-mediated neuroblastoma cell survival." (PMID 27572323, 2016). "HDAC10 depletion in neuroblastoma cells interrupted autophagic flux and induced accumulation of autophagosomes, lysosomes and a substrate of the autophagic degradation pathway, p62/SQSTM1." (PMID 25695609, 2015). "As a result, inhibition of HDAC10 autophagy may be a unique method for sustaining chemotherapeutic efficacy, particularly in the treatment of advanced-stage neuroblastoma." (PMID 39409979, 2024). "Reports in PNAS and Autophagy illustrate that HDAC10 could promote autophagy‐mediated survival in neuroblastoma and improve treatment response of advanced neuroblastomas." (PMID 34308568, 2021). "Authors suppose that combination of HDAC10 with doxorubicin may be effective in neuroblastoma therapy." (PMID 32575682, 2020). "We demonstrate that targeting HDAC10 sensitizes neuroblastoma cells to doxorubicin by inhibiting drug efflux via lysosomal exocytosis and enhancing DNA double-strand breaks, thereby promoting tumor cell death in chemotherapy resistant neuroblastoma models." (PMID 29968769, 2018). "Our data suggest that lysosomal exocytosis under doxorubicin treatment is important for cell survival and that inhibition of HDAC10 further induces DNA double-strand breaks (DSBs), providing additional mechanisms that sensitize neuroblastoma cells to doxorubicin." (PMID 29968769, 2018). "HDAC10 inhibition increases intracellular accumulation of chemotherapeutics through interference with lysosomal homeostasis, ultimately leading to cell death in cultured neuroblastoma cells." (PMID 29947893, 2018). "HDAC10 depletion by inhibition using the class IIb inhibitors bufexamac and tubastatin as well as knockdown disrupted the autophagic flux and induced accumulation of autophagosomes, lysosomes, and p62 in neuroblastoma cells." (PMID 30563957, 2017). "However, knockdown of HDAC10 in neuroblastoma cells increased the accumulation of AVOs, led to accumulation of ROS, and impaired efficient fusion of autophagosomes with lysosomes under the same conditions." (PMID 25915736, 2015). "Hence, suppression of HDAC10 autophagy may be a novel strategy to sustain the cytotoxicity of cancer chemotherapy, especially for the treatment of advanced-stage neuroblastoma." (PMID 37533111, 2023). "Unlike HDAC6 as an acetyllysine deacetylase, HDAC10 is an N8-acetylspermidine deacetylase, which is associated with dysregulated polyamine metabolism and relevant neoplastic diseases, such as colon cancer, prostate cancer and neuroblastoma." (PMID 37533111, 2023). "Down-regulation of HDAC10 may restore the sensitivity of doxorubicin in neuroblastoma." (PMID 33997894, 2021).
neuroblastoma (continued). "HDAC10 inhibition combined with doxorubicin administration kills neuroblastoma but not non-malignant cells by impeding drug efflux and enhancing DNA damage." (PMID 35359455, 2022). "Taken together, we demonstrate that HDAC10 inhibition in combination with doxorubicin kills neuroblastoma, but not non-malignant cells, both by impeding drug efflux and enhancing DNA damage, providing a novel opportunity to target chemotherapy resistance." (PMID 29968769, 2018).
lung carcinoma (18 papers, 2008 to 2024). "HDAC10 has been reported to be highly expressed in lung cancer tissues where it is associated with a poor prognosis." (PMID 31949209, 2020). "In lung cancer, decreased HDAC10 is associated with the advanced stage and adverse outcome." (PMID 30029622, 2018). "While HDAC10 depletion caused a significant SPARC upregulation in melanoma cells, SPARC expressions in lung cancer cells were too low to effectively gauge any change brought about by HDAC10 depletion." (PMID 38650694, 2024). "The sequencing of tumoral samples from lung cancer patients has shown a strong correlation between the expression of class II HDACs, particularly a low HDAC10 expression, and prognosis." (PMID 39409979, 2024). "Consistent with our results that HDAC10 represses SPARC expression in melanoma cells, in an RNA-seq analysis, SPARC is one of the top upregulated genes upon HDAC10 depletion in H1299 lung cancer cells." (PMID 38650694, 2024). "HDAC10 deletion also recruits massive macrophages (especially M2 macrophages) into the lung cancer microenvironment." (PMID 33997894, 2021). "We observed that HDAC10 expression in lung cancer tissue is significantly higher than that in corresponding para-cancer tissue." (PMID 32373519, 2020). "These animal experiments confirmed that HDAC10 promotes and is required for tumour growth in vivo, and these results were consistent with previous observations regarding the function of HDAC10 in lung cancer cell lines." (PMID 27449083, 2016). "In the present study, we analysed HDAC10 expression in a lung cancer tissue microarray and found that it was highly expressed in the cytoplasm of lung cancer cells." (PMID 27449083, 2016). "We demonstrated that HDAC10 promotes lung cancer cell growth and survival and AKT is potentially involved in the process." (PMID 27449083, 2016). "Given the elevated expression of HDAC10 in lung cancer tissue, we evaluated the effects of HDAC10 overexpression on cell growth, cell cycle activity and apoptosis in lung cancer cells." (PMID 27449083, 2016). "Further investigation revealed that HDAC10 promotes lung cancer growth, in which AKT is potentially involved." (PMID 27449083, 2016). "HDAC10 resides mainly in the cytoplasm of lung cancer cells but resides in the nucleus of adjacent normal cells." (PMID 27449083, 2016). "To verify this observation, we examined the distribution of endogenous HDAC10 in multiple lung cancer cell lines, including the A549, H385 and H460 cell lines, and a normal lung cell line, 16HBE." (PMID 27449083, 2016). "In summary, we observed the increased expression and distinct distribution of HDAC10 in lung cancer cells and identified an intrinsic and critical sequence that is associated with HDAC10 nuclear localization." (PMID 27449083, 2016). "The tissue microarray data and cell function analysis results suggest that HDAC10 plays an important role in cell growth and survival in lung cancer." (PMID 27449083, 2016). "Functional analysis revealed that HDAC10 promoted lung cancer cell growth and that its knockdown induced cell cycle arrest and apoptosis." (PMID 27449083, 2016). "Our study demonstrated that HDAC10 localizes and functions in the cytoplasm of lung cancer cells, thereby underscoring its potential role in the diagnosis and treatment of lung cancer." (PMID 27449083, 2016). "To determine the physiological significance of HDAC10 in human lung cancer, we analysed HDAC10 protein levels in an NSCLC tissue array." (PMID 27449083, 2016). "Further examinations revealed that HDAC10 resides in the cytoplasm in multiple lung cancer cell lines, including the A549, H358 and H460 cell lines, but mainly resides in the nucleus of normal lung epithelial 16HBE cells." (PMID 27449083, 2016). "In this study, we found that HDAC10 is highly expressed in lung cancer cells and is required for tumour growth and survival." (PMID 27449083, 2016).